AFP (alpha fetoprotein)
Diseases named in the same sentence as AFP in open-access papers (continued):
Sharing a sentence is not in itself a finding about the gene and the disease.
yolk sac tumor (continued). "Ovarian yolk sac tumors, though rare, require a high index of suspicion, especially in pediatric patients presenting with abdominal masses and elevated AFP levels." (PMID 39687655, 2024). "The pathology report confirmed a successful and complete (R0) resection of a hepatoid type pleural yolk sac tumor, as evidenced by positive staining for perkeratine, Alpha-Fetoprotein, and Glypican-3." (PMID 38622623, 2024). "A nomogram based on age, AFP levels, and ultrasound blood flow signals can effectively predict the probability of testicular yolk sac tumor preoperatively, aiding in clinical decision-making and patient counseling." (PMID 39606696, 2024). "Only the patient with yolk sac tumor in the retroperitoneum had a highly elevated AFP preoperatively." (PMID 39020389, 2024). "Age, serum AFP levels, maximum tumor diameter, and ultrasound blood flow signals are key predictive factors for testicular yolk sac tumors in children." (PMID 39606696, 2024). "The heterogeneous morphology constituting of papillary and solid patterns noted within the same tumor coupled with immunohistochemical positivity for AFP favored a diagnosis for a NSGCT with yolk sac tumor as the most likely possibility in this scenario." (PMID 39363907, 2024). "Endometrial carcinoma with “yolk sac tumor differentiation” (EC-YST) is another rare entity which shows at least partial overlap with AFP+ EC." (PMID 39408649, 2024). "One interesting note about AFP is that its levels are commonly analyzed in the management of other forms of malignancy, like testicular cancer, yolk sac tumors, or extragonadal germ cell tumors, yet it is still widely advocated as a biomarker for HCC." (PMID 39200161, 2024). "A nomogram based on age, AFP levels, and ultrasound blood flow signals effectively predicted the probability of yolk sac tumor in children, with an accuracy of 0.98 (95% confidence interval: 0.984–1.003)." (PMID 39606696, 2024). "Patients with testicular yolk sac tumors were younger (median age: 14.0 vs. 34.0 months, P = 0.001) and had a higher incidence of elevated AFP levels (93.1% vs. 2.2%, P < 0.001)." (PMID 39606696, 2024). "AFP (P = 0.031) and ultrasound blood flow signals (P = 0.001) were identified as significant predictors of testicular yolk sac tumors in children." (PMID 39606696, 2024). "Among patients with serum AFP levels greater than 3000, 71.42% (5 out of 7) had pure yolk sac tumor, while 29.58% (2 out of 7) had a combination of 90% yolk sac tumors and 10% mature teratomas." (PMID 38966065, 2024). "Alpha-fetoprotein (AFP) is the most widely used serum biomarker for identifying testicular yolk sac tumors in children." (PMID 39606696, 2024). "NGGCTs secrete alpha-fetoprotein (AFP), mainly produced by yolk sac tumors and beta-human chorionic gonadotropin (β-HCG), which can be secreted by choriocarcinoma." (PMID 38012690, 2023). "A stable increase in serum AFP is seen in pure yolk sac tumors and GCTs containing a yolk sac tumor." (PMID 37138865, 2023). "Nevertheless, increased serum levels of AFP in patients with apparent immature teratoma should prompt additional investigation and search with a focus on yolk sac tumor, the presence of which would change the diagnosis to mixed germ cell tumor." (PMID 37508611, 2023). "The detection and secretion of AFP and β-hCG in body fluids is restricted to specific subtypes, with levels raised predominantly in tumors containing a yolk sac tumor and choriocarcinoma histopathology, respectively." (PMID 35204369, 2022). "Correspondingly, our assessment is that the probability of a multiply undiagnosed yolk sac tumor component among the ImT cases with AFP elevation is quite low." (PMID 35205726, 2022). "AFP was elevated in 5/39 patients (12.8%): two patients had an immature teratoma, one patients had a yolk sac tumor, one patient had a sertoli-cell tumor, and one patient had ovarian necrosis, respectively." (PMID 35937851, 2022).
yolk sac tumor (continued). "An elevated AFP was seen in two patients with yolk sac tumors diagnosis and normalized after surgery." (PMID 35204369, 2022). "In fact, elevated AFP should trigger the pathologist to search for yolk sac tumor foci, easily overlooked admixed between other tumor components." (PMID 33800799, 2021). "In patients with HCC metastasis to the ovary, hepatoid yolk sac tumor and primary hepatoid carcinoma of the ovary, both AFP-producing ovarian tumors, should be considered in differential diagnosis." (PMID 33978943, 2021). "These include hepatoid carcinoma, unspecified adenocarcinoma with AFP production, and yolk sac tumor." (PMID 34977100, 2021). "AFP is detected in endodermal sinus tumors such as yolk sac tumors, and β-HCG is a marker of choriocarcinomas." (PMID 34829327, 2021). "At the time of PD, elevated AFP was detected in all the five patients with yolk sac tumor, two patients with teratoma and one patient with mixed GCT." (PMID 32766147, 2020). "Increased levels of AFP in serum/CSF indicate that the GCT contains a component of a yolk sac tumor or immature teratoma." (PMID 32868820, 2020). "The patient with combined endodermal sinus tumor and embryonal carcinoma had very high levels of preoperative AFP (4899 ng/ml), beta hCG (3751 IU/L) and CA125 (259 U/ml)." (PMID 31897390, 2019). "A non-HIV-infected man with unilateral cryptorchidism presented with a rapidly growing mass for 6 months and large (17 cm × 19 cm × 35 cm) mixed GCTs (mostly yolk sac tumors: 90–95%) in the retroperitoneum with elevated levels of AFP (120,000 ng/mL)." (PMID 30885154, 2019). "In the early experiments, Con A affinity chromatography exhibited different binding to AFP isolated from amniotic fluid, foetal serum, liver cancer serum and yolk sac tumour serum." (PMID 31652641, 2019). "AFP is a 70 kDa glycoprotein produced by cells of the yolk sac tumour and rarely by embryonal carcinoma." (PMID 31275973, 2019). "The biological background for this finding is probably the high incidence of AFP-producing yolk sac tumours and bHCG producing choriocarcinomas in the younger patients while the nonsecreting seminomas predominate in the older age groups." (PMID 31275973, 2019). "An analysis of AFP-L3%, a fraction of AFP binding to LCA, appears to be a better biomarker for identifying a recurrence of the yolk sac tumour than an analysis of AFP in serum for a neo-natal patient." (PMID 31652641, 2019). "Serum elevation of alpha fetoprotein and beta human chorionic gonadotropin is common in mixed germ cell tumours, correlating with the presence of yolk sac tumour elements and syncytiotrophoblastic cells, respectively." (PMID 31581033, 2019). "In our case, the serum marker AFP was highly elevated, i.e., 34,222 ng/ml, predominantly indicating the presence of a yolk sac tumor." (PMID 30885154, 2019). "Nevertheless, some authors argue for the existence of yolk sac tumour of the endometrium in postmenopausal patients based on AFP expression." (PMID 28494767, 2017). "In 1 case of yolk sac tumor, on the basis of the preoperative biopsy and high levels of AFP, we performed initial surgical treatment because the tumor was anatomically thoracically resectable." (PMID 28634489, 2017). "The elevation of AFP in serum of people older than one year is indicative of either HCC or yolk sac tumor." (PMID 29434637, 2017). "Yolk sac tumors secrete substances such as AFP, B-hCG, and cytokeratin (CEA), which can be measured in the serum." (PMID 27144043, 2016). "Yolk sac tumors immunohistochemical testing is positive for AFP, glypican-3, SALL4, and placental alkaline phosphatase." (PMID 27144043, 2016). "In summary, testicular yolk sac tumor presents as a painless scrotal mass and an increased serum AFP level (>100 ng/mL)." (PMID 25547829, 2014).
yolk sac tumor (continued). "Testicular yolk sac tumors frequently secrete high concentrations of AFP; therefore, AFP is considered important in the diagnosis and follow-up of the tumors." (PMID 25547829, 2014). "In our study only in 14 cases of yolk sac tumor and one patient of immature teratoma, AFP was elevated, and also BHCG was increased in one case of choriocarcinoma." (PMID 25755868, 2014). "Testicular yolk sac tumor presents as a painless scrotal mass, increased serum AFP levels, and a solid mass on ultrasound." (PMID 25547829, 2014). "In the current study, serum AFP levels were measured 2 weeks after surgery in 15 pediatric patients treated for testicular yolk sac tumor." (PMID 25547829, 2014). "Evidence suggests that infants aged younger than 1 year with serum AFP levels >100 ng/mL should be presumed to have a yolk sac tumor, and that serum AFP levels should be monitored postoperatively to indicate yolk sac tumor recurrence during follow-up." (PMID 25547829, 2014). "A markedly elevated serum alpha-fetoprotein (AFP) level to 18.178 ng/ml oriented toward the diagnosis of an ovarian yolk sac tumor." (PMID 24251245, 2013). "Immunohistochemical expression of alpha fetoprotein (AFP) can be used for the diagnosis of yolk sac tumours." (PMID 23066729, 2012). "Pathology revealed evidence of a yolk sac tumor, and laboratory results showed a marked elevation of serum alpha-fetoprotein (AFP) of up to 16780 ng/ml with normal serum levels of β-human chorionic gonadotropin." (PMID 20062625, 2009). "Positive rate of AFP was 11.8% in dysgerminoma, 100% in yolk sac tumor and 61.9% in immature teratoma." (PMID 17587461, 2007). "Although imaging findings may be inconclusive, in young patients presenting with a large, predominantly solid ovarian mass and elevated serum AFP levels, the possibility of a yolk sac tumor should be strongly considered." (PMID 40723200, 2025). "Especially for patients with simple yolk sac tumors, AFP levels can reach 10000 μ G/L or above." (PMID 41018086, 2025). "First, yolk sac tumors (YSTs) typically occur in young women (usually before the age of 30) and commonly present with lower abdominal pain, palpable masses, and markedly elevated AFP levels." (PMID 40919162, 2025). "However, yolk sac tumors also exhibit microcystic and endodermal sinus like structures, and express AFP, SALL4." (PMID 40115014, 2025). "Additionally, in our study, three yolk sac tumors presented with normal AFP levels, underscoring the limitations of relying solely on AFP as a predictor for testicular yolk sac tumor." (PMID 39606696, 2024). "However, elevated serum AFP was noticed in 27/29 cases (93.1%) for the yolk sac tumor group while the incidence was 2.2% (2/90) in the benign group (P < 0.001)." (PMID 39606696, 2024). "Furthermore, laboratory tests revealed elevated alpha-fetoprotein levels (α-FP) of 68.300 μg/l, further confirming the diagnosis of a yolk sac tumor." (PMID 38622623, 2024). "The patient's age, serum AFP levels, maximum tumor diameter, ultrasonic echo, and blood flow signal were identified as predictive factors for differentiating between testicular benign and yolk sac tumors." (PMID 39606696, 2024). "The mature teratoma does not cause an elevation of tumor markers, whereas immature teratoma could be associated with elevated alpha-fetoprotein (AFP), especially if it contains microscopic foci of the yolk sac tumor." (PMID 39099946, 2024). "Serum AFP is a crucial marker for diagnosing yolk sac tumors in children." (PMID 39606696, 2024). "Alpha-fetoprotein (AFP), a fetal serum protein, may be useful as a tumor marker for the detection of malignancies such as yolk sac tumors (YST)." (PMID 37367072, 2023). "The AFP concentration in a pure yolk sac tumor is typically greater than 500 mg/L." (PMID 37215600, 2023). "Endodermal sinus tumors occur at a younger age and can occur in children and women of childbearing age, with significant enhancement and may be accompanied by elevated AFP." (PMID 38097964, 2023).
yolk sac tumor (continued). "Therefore, Glypican-3 and AFP were used to check for the presence of yolk sac tumors in the patient’s biopsy." (PMID 36805679, 2023). "According to the standards of the international society of pediatric oncology (SIOP) and children's oncology group (COG), NGGCTs can be defined clinically by the elevation of AFP level (AFP >10 mg/L) in serum or CSF, which includes yolk sac tumors, immature teratoma, and embryonic carcinoma." (PMID 37215600, 2023). "AFP can be a marker of immature ovarian teratoma, yolk sac tumor, and embryonal carcinoma." (PMID 35937851, 2022). "Serum AFP > 100 ng/ml was consistently strongly correlated with yolk sac tumor." (PMID 36601033, 2022). "AFP is known to be elevated in embryonal carcinomas and yolk sac tumors." (PMID 36550425, 2022). "AFP was increased in all cases of endodermal sinus tumor or teratocarcinomas." (PMID 34249791, 2021). "AFP has been reported not only in APA but also in yolk-sac tumors or some neuroendocrine tumors." (PMID 33996549, 2021). "Yolk sac tumors can secrete AFP and choriocarcinomas can release hCG." (PMID 34829327, 2021). "Whether AFP+ EC and “AFP-producing carcinomas” of other organs such as stomach and lung should be classified as “carcinomas” or “yolk sac tumors” is an unresolved nosological problem." (PMID 34977100, 2021). "Therefore, at least some of these “glandular yolk sac tumors” can be regarded as the same tumors that are reported under the name of AFP+ EC." (PMID 34977100, 2021). "Several arguments can be put forward for the case of separation of AFP+ EC from yolk sac tumor." (PMID 34977100, 2021). "In our case, both yolk sac tumor and embryonal carcinoma components showed diffused AFP expression." (PMID 32064359, 2020). "Yolk sac tumors produce AFP, while germinomas and choriocarcinomas, produce β-HCG." (PMID 33005196, 2020). "In addition, these two biomarkers are limited to some types of TC (AFP for yolk sac tumour and hCG for TC choriocarcinoma)." (PMID 31652641, 2019). "AFP was raised in patients with endodermal sinus tumor (189.6 ng/ml–940 ng/ml)." (PMID 31897390, 2019). "Although serum AFP level is apparently low in adults, it may significantly increase in the pathological conditions including yolk sac tumors, hepatocellular carcinoma, and cirrhosis and hepatitis." (PMID 27995033, 2016). "In conclusion, clinicians should be aware that there are certain tumors besides HCC and endodermal sinus tumors, such as hepatic cavernous hemangioma, that may produce AFP in adults." (PMID 25624892, 2015). "However, raised levels of α-fetoprotein (AFP), observed in 90% of patients with yolk sac tumors, can help distinguish yolk sac tumors from other tumors." (PMID 26137335, 2015). "AFP was elevated in 14 cases of yolk sac tumor and one patient of immature teratoma." (PMID 25755868, 2014). "In some patients with raised serum levels of AFP, yolk sac tumor elements may have been missed by the pathologist, even though the pathologists classified all tumors included in this series as an immature teratoma and did not report the presence of yolk sac elements in the tumor." (PMID 41118662, 2026). "Notably, AFP was within the normal range for infants under 1 year, and imaging revealed heterogeneous, predominantly cystic lesions, favoring a benign teratoma over yolk sac tumor or malignant germ cell tumor." (PMID 41255769, 2025). "However, AFP levels can be elevated in infants and other diseases, and some patients with yolk sac tumors may even present with normal AFP levels." (PMID 39606696, 2024). "Therefore, AFP staining remains a good protocol for identifying yolk sac tumors." (PMID 37138865, 2023). "Alpha-fetoprotein (AFP), secreted by yolk sac tumor (YST) cells, is a crucial biomarker for both diagnosis and prognosis, with approximately 80% of patients exhibiting elevated AFP levels." (PMID 41235014, 2025).
yolk sac tumor (continued). "AFP is a glycogen protein, and in MOGCT (such as yolk sac tumors, embryonic cancers, and mixed tumors), AFP is usually greater than 1000 μ G/L." (PMID 41018086, 2025). "A panel including CD117, SOX2, and CD30 can distinguish between an EC and dysgerminoma, and a panel including AFP, glypican-3, OCT4, and CD30 can distinguish between an EC and a yolk sac tumor." (PMID 36140449, 2022). "The results of postoperative pathological examination confirmed giant testicular yolk sac tumor (T1N0M0S1, Stage Is) and was positive for AFP and SALL4 in immunohistochemistry staining." (PMID 36605756, 2022). "The serum markers used are alpha-fetoprotein, hCG and LDH, however alpha-fetoprotein is only seen in yolk-sac tumor and teratomas whilst hCG is expressed by trophoblasts only." (PMID 33251139, 2020). "Alpha-fetoprotein (AFP) is a useful tumor marker for ovarian germ cell tumors, particularly yolk sac tumor (YST)." (PMID 29933751, 2018). "One patient with an endodermal sinus tumor (volume = 40 cm, stage III), had high levels of serum tumor biomarkers (AFP >1000 ng/ml, CA125 >600 U/ml)." (PMID 23826706, 2013). "They reported that in patients with serum AFP or HCG < 9.9 the main histological component was germinoma, 10.0 < AFP or HCG < 999 patients had teratomas, and 1000 < AFP or HCG patients had highly malignant yolk sac tumors or choriocacinomas." (PMID 22286191, 2012). "Many malignant tumors with AFP producing and hepatoid features resembling HCC, such as hepatoid adenocarcinoma of the stomach and primary hepatoid yolk sac tumor (H-YST) of ovary and testis, especially the latter, express AFP, Hep Par 1 and GPC3." (PMID 21443783, 2011). "AFP levels are significantly elevated in approximately 90% of patients with yolk sac tumors, meaning that in about 10% of these patients, AFP levels do not increase." (PMID 39606696, 2024). "Still AFP is highly specific for yolk sac tumors and is not expressed or only occasionally expressed in embryonic tumors, teratomas and other tumor types." (PMID 37138865, 2023). "When young teenagers complain of acute lower abdominal pain with elevated AFP, but there was no lesion in bilateral ovaries and fallopian tubes, we must think about the possibility of endodermal sinus tumors." (PMID 37474890, 2023). "No specific marker has been discovered for extragonadal yolk sac tumors, but alpha fetoprotein (AFP) is a relatively characteristic marker for the epithelial component of yolk sac tumors in general." (PMID 37138865, 2023). "Yolk sac tumors produce AFP, and even if it is not pathognomonic, its serum levels are useful for the diagnosis of a primary ovarian malignancy, its metastases or its recurrence." (PMID 36140449, 2022). "AFP and β-hCG are secreted by non-seminomatous tumors, yolk sac tumors and syncytio-trophoblasts of choriocarcinoma, whereas LDH is also secreted by seminomas." (PMID 35204369, 2022). "For this reason, elevated AFP levels are not found in pure seminoma or trophoblastic tumors, but in 90% of yolk sac tumors and sometimes in embryonal carcinomas." (PMID 32235691, 2020). "We stratified the TCGA testicular cancer cohort into seminomas (SOX17+) and non-seminomas (SOX2+ (EC), AFP+ (yolk-sac tumor), beta-hCG+ (choriocarcinomas)." (PMID 32272809, 2020). "The biosynthesis of AFP is confined to yolk sac tumour components of nonseminomatous GCTs while bHCG is produced in syncytiotrophoblastic-like cells occurring in both nonseminomas and seminomas." (PMID 31275973, 2019). "In our study, strong upregulation of AFP in the OCT3/4 negative TCam-2-ΔSOX2 subpopulation is indicative for development of a yolk-sac tumor." (PMID 27283990, 2016). "No statistical difference was found in serum AFP level 2 weeks after yolk sac tumor resection compared with that preoperatively." (PMID 25547829, 2014).